KCNQ2 (potassium voltage-gated channel subfamily Q member 2)
Diseases named in the same sentence as KCNQ2 in open-access papers (continued):
Sharing a sentence is not in itself a finding about the gene and the disease.
epilepsy (continued). "In humans KCNQ2/3 heteromeric channels form an M-current that acts as a brake on neuronal excitability, with mutations causing a form of epilepsy." (PMID 23638087, 2013). "For example, a combination of mutant alleles in Scn2a and Kcnq2 resulted in a much more severe epilepsy phenotype than when mutations were only present in a single gene." (PMID 19837565, 2009). "KCNQ2-associated epilepsies encompass a wide spectrum of epilepsy syndromes, including self-limited early-onset epilepsies (where seizure remission is seen in the majority of affected children), and KCNQ2-DEE (where seizure freedom is not uncommon by adolescence or early adulthood)." (PMID 40381056, 2025). "Moreover, KCNQ2 has also been reported to play a critical role in modulating susceptibility to seizures and epilepsy." (PMID 41155561, 2025). "KCNQ2 mutations can cause epilepsy in infants with different degrees of seizure severity." (PMID 40236662, 2025). "Furthermore, sodium channel blockers present favorable responses to many potassium channel-related epilepsies, such as those caused by KCNQ2." (PMID 40230348, 2025). "The therapeutic potential of donepezil may also be of great value in children with epilepsy caused by GoF variants in KCNQ2, since its administration was recently shown to confer robust protection against induced seizures in a mouse model of Dravet syndrome." (PMID 39175503, 2024). "Kcnq2 deficiency in pyramidal neurons increased neuronal excitability, resulting in epilepsy." (PMID 39569070, 2024). "One of the epilepsy-associated genes (KCNQ2) has two orthologues in zebrafish (kcnq2a and kcnq2b)." (PMID 38474238, 2024). "Moreover, double mutant mice carrying the Scn2aQ54 mutation together with either of the Kcnq2 mutations (Kcnq2VM or Kcnq2Szt1) exhibited severe epilepsy with early onset seizures and lethality by 3 weeks of age." (PMID 39513870, 2024). "Examples of a genetic link include epilepsy associated with KCNQ2, CDKL5, and SCN1A mutations." (PMID 37928141, 2023). "Other genetic epilepsies that can benefit from precision therapy include KCNQ2 (carbamazepine, phenytoin), GLUT1 deficiency, SLC2A1 or CDKL5 (ketogenic diet), PCDH19 (clobazam), mutations in KCNQ2, SCN2A, and SCN8A (ion sodium channel blockers), and mTORopathies (mTOR inhibitors)." (PMID 36980114, 2023). "The emerging Kcnq2 genotype-phenotype relationship suggests loss of function variants result in neonatal epilepsy, whereas gain-of-function variants are associated with more severe symptoms including profound developmental delay, severe hypoventilation and early mortality." (PMID 38052789, 2023). "By comparison, the response to LEV was inferior in PRRT2- and KCNQ2-related epilepsy, and it may probably be useful for SCN1A-associated epilepsy." (PMID 35720076, 2022). "Understanding which parameters are affected could provide insight into what region may cause channel dysfunction, as exemplified in the epilepsy-associated uncoupling KCNQ2-R214W mutation." (PMID 35642783, 2022). "Hundreds of genetic variants in KCNQ2 encoding the voltage-gated potassium channel KV7.2 are associated with early onset epilepsy and/or developmental disability, but the functional consequences of most variants are unknown." (PMID 35104249, 2022). "To demonstrate that automated patch clamp recording is a valid approach for evaluating the functional consequences of epilepsy-associated KCNQ2 variants, we compared data we obtained for 18 variants to results from prior voltage-clamp recording in either mammalian cells or Xenopus oocytes." (PMID 35104249, 2022). "We present a family case of neonatal-onset KCNQ2-related epilepsy due to a novel intronic mutation." (PMID 35911888, 2022). "Additionally two likely pathogenetic variants SCN1B (rs 150,721,582) and the KCNQ2 (rs771211103) genes have been implicated in childhood epilepsies." (PMID 35177115, 2022). "Loss of function of KCNQ2 or KCNQ3 causes epilepsy in humans and mice." (PMID 35188099, 2022).
epilepsy (continued). "In three other patients who presented primarily with epilepsy, gene sequencing identified de novo KCNQ2 variants, for which anticonvulsant treatment with sodium channel blockers is highly recommended and reduces the neurodevelopmental impairment associated with the disease." (PMID 32718099, 2020). "Pathogenic variants in KCNQ2 cause early-onset epilepsies with wide phenotypic heterogeneity." (PMID 33013448, 2020). "Interestingly, increasing evidence has shown that the gain of function in potassium channel variants is actually associated with epilepsy, including KCNQ2 and KCNQ3." (PMID 31652643, 2019). "We also found that KCNQ2‐associated epilepsy patients had varied outcomes." (PMID 31199083, 2019). "RTG or other Kv7.2-channel openers may be considered as first-line antiepileptic treatments for epilepsies resulting from KCNQ2 mutations." (PMID 26910900, 2016). "However, a few KCNQ2 mutations have recently been found to cause early infantile epileptic encephalopathy, which is a malignant epilepsy phenotype." (PMID 24586341, 2014). "Therefore, KCNQ2 mutations induce a range of epilepsy phenotypes, and our understanding of this gene is still limited." (PMID 24586341, 2014). "The precise percentage of neonates and children with KCNQ2‐associated epilepsy is unknown." (PMID 31199083, 2019). "Although other mechanisms, such as increased GABAergic inhibition, have been suggested, a comparable restoration of the M-current in human instances of monogenic KCNQ2 mutations might well contribute to the developmental recovery from the transient epilepsies seen in many cases of BFNS." (PMID 23977150, 2013). "The established knock-in models provide powerful tools for elucidating disease mechanisms of EIDEE and SeLFNIE, and developing targeted therapies for KCNQ2-related epilepsies." (PMID 41742307, 2026). "KCNQ2 and KCNQ3 play a critical role in modulating susceptibility to seizures, and their mutations cause heterogeneous epilepsy phenotypes." (PMID 41155561, 2025). "This is achieved by activating KCNQ2/3 (Kv7.2/7.3) potassium channels, ultimately helping to control the occurrence of epilepsy." (PMID 40667464, 2025). "Our study underscores the extreme variability in the phenotypic spectrum of KCNQ2-related epilepsies and unveils the prospect of its inclusion in screening panels for EAFs." (PMID 39796146, 2024). "Our study underscores the extreme variability in the phenotypic spectrum of KCNQ2-related epilepsies, ranging from self-limited neonatal seizures to severe developmental encephalopathies." (PMID 39796146, 2024). "The overall estimated annual incidence of single-gene epilepsies in this population was 1 per 2120 live births (47.2/100 000; 95% CI 36.9 to 57.5), with pathogenic variants in SCN1A, PCDH19, CDKL5 and KCNQ2, having the highest incidence for DEE." (PMID 39613335, 2024). "The three KCNQ2 cases identified in our study highlight the importance of including this gene in any DEE or Epilepsy panel, as it is relevant and potentially allows clinicians to offer precision therapy." (PMID 38702429, 2024). "For example, KCNQ2, KCNQ3, SCN1A, SCN2A, and SCN8A are associated with phenotypes ranging from self-limited epilepsies with normal developmental outcome to intermediate severity conditions to drug-resistant epilepsies with profound developmental impairment." (PMID 37596007, 2023).
epilepsy (continued). "Automated patch-clamp recordings enable high-throughput evaluation of epilepsy-associated KCNQ2 variants, expanding our understanding of the molecular basis of KCNQ2-related epilepsy." (PMID 37497102, 2023). "However, the drug may have potential value as targeted therapy for KCNQ2-associated epilepsy." (PMID 35104249, 2022). "Although epilepsy caused by the KCNQ2, KCNQ3, PRRT2, SCN2A and SCN8A gene are relatively benign, in our study, more than 18 genes caused epilepsy accompanied by the intellectual disability and more than 14 genes caused syndromes with epilepsy." (PMID 35571021, 2022). "SHR model can be associated with various central nervous system (CNS) indications such as KCNQ2-related epileptic encephalopathy or various orphan forms of epilepsy, however, it is extensively used as the gold standard rodent model of ADHD." (PMID 35401075, 2022). "Prospective studies are needed to analyze and compare the effects of standardized treatment protocols with VItB6 in neonatal epilepsies in general and in those KCNQ2-related in particular." (PMID 35401395, 2022). "Our findings contribute to understanding the spectrum of KCNQ2 channel dysfunction in monogenic epilepsy and reveal variable retigabine responsiveness among the studied variants." (PMID 35104249, 2022). "Five reports have openly disclosed various degrees of a successful response to PN/PLP in KCNQ2-related epilepsies." (PMID 35401395, 2022). "The patient's family history was positive for epilepsy both in the maternal and paternal line; in particular, the father was diagnosed with a KCNQ2-related-epilepsy treated with Valproate (VPA) and Phenobarbital (Pb)." (PMID 35401395, 2022). "Amounting evidence arising by next-generation sequencing techniques have led to the definition of new phenotypes, such as neonatal epileptic encephalopathy (NEE), expanding the spectrum of KCNQ2-related epilepsies." (PMID 35401395, 2022). "Eighty-one epilepsy-related genes were detected; the gene most frequently detected was KCNQ2 (nine times), followed by PRRT2 (seven times), SCN1A (six times), SCN2A (five times), SPTAN1 (four times), and TSC2 (four times)." (PMID 35571021, 2022). "Another successful combination included the KCNQ2-5/Kv7.2–7.5 channel opener, and FDAapproved epilepsy treatment, retigabine." (PMID 35326650, 2022). "Most patients with KCNQ2-related disorder were self-limited epilepsy, but most of them had a severe impairment development." (PMID 34711204, 2021). "Ezogabine, an activator of Kv7.2–5 subunit-containing channels that is approved for epilepsy in adults, has been shown to reverse effects of KCNQ2 encephalopathy variants in patch clamp experiments." (PMID 33041849, 2020). "Mutations of the KCNQ2 and KCNQ3 voltage‐gated potassium channel genes have been implicated in the pathophysiology of a spectrum of seizure disorders, ranging from pharmacoresponsive self‐limiting neonatal epilepsy to severe epileptic encephalopathy." (PMID 33336127, 2020). "CSWS has been described in various genetic conditions, including common epilepsy-related ion channel genes like SCN2A or KCNQ2, as well as the N-methyl D-aspartate receptor subunit gene GRIN2A, that show overlapping expression at neuronal synapses." (PMID 33126500, 2020).
epilepsy (continued). "Epilepsy is linked to mutations in KCNQ channels, and CaM is one of the auxiliary proteins that are necessary for activation of the KCNQ2 channel." (PMID 30213136, 2018). "Retigabine (ezogabine), is a drug primarily acting as a positive allosteric modulator of KCNQ2-5 (Kv7.2–7.5) ion channels: it is the first neuronal potassium (K + ) channel opener licensed for the treatment of epilepsy." (PMID 28082152, 2018). "Mutations in KCNQ2 and KCNQ3 subunits underlie various forms of epilepsy, including early infantile epileptic encephalopathy, benign familial neonatal seizures, and other miscellaneous early onset encephalopathies." (PMID 30242262, 2018). "Sodium channel blockers including carbamazepine and phenytoin should also be considered as first-line treatment in patients with KCNQ2-related epilepsy." (PMID 28082152, 2018). "Retigabine, a positive allosteric modulator of KCNQ2, has recently been licenced for the treatment of epilepsy." (PMID 28334860, 2017). "The HAR1A gene is considered an accelerated evolution gene for human brain development with molecular defects of the gene leading to psychotic and disruptive disorders; the genes CHRNA4 and KCNQ2 also deleted have been associated with ASD and epilepsy." (PMID 27651829, 2016). "KCNQ2/3 openers, such as ICA-27243, can shift the activation of KCNQ2/3 to a hyperpolarized potential and prevent epilepsy." (PMID 25904892, 2015). "ICA-105665, a new generation of anti-seizure drug targeting KCNQ2/3 channels, was tested for efficacy in several epilepsy models because of its selectivity for potassium channels." (PMID 25904892, 2015). "Potassium ion channels are involved in mammalian epilepsy, and Kcnq2 heterozygous mutant mice demonstrate its role in the control of neuronal excitability." (PMID 20805988, 2010). "Our model adds to the growing list of other specific human epilepsy knockin mice, including the Gabrg2, Kcnq2, Kcnq3, Scn1a and Chrna4 mice, to report a clear-cut genotype to phenotype seizure susceptibility." (PMID 19763161, 2009). "Variants in KCNQ2 are one of the most common monogenic causes of epilepsy in children, but are not encountered frequently in adults undergoing genetic testing." (PMID 40381056, 2025). "The epilepsy risk gene KCNQ2 was not rescued (avg log2FC −.763 corP < .01), whereas SYNE2 was (corP > .675)." (PMID 40704780, 2025). "Based on the findings regarding the structural changes in the interaction between mutant KCNQ2 and PIP2, we hypothesize that pathogenic mutations may contribute to the development of epilepsy in children by weakening the binding of PIP2 to mutant KCNQ2." (PMID 40342533, 2025). "A well-known example is the KCNQ2/KCNQ3 heterotetramer, which predominates in the adult central nervous system and is crucial in maintaining neuronal excitability and preventing hyperexcitability associated with epilepsy." (PMID 39971736, 2025). "The phenotypic spectrum of KCNQ2-related epilepsies is now expanding." (PMID 39796146, 2024). "KCNQ2 and ASH1L are linked to epilepsy and autism spectrum disorder." (PMID 38283851, 2024). "In addition, the proband of family 2 was treated with phenobarbital, which is one of the most effective anti-seizure medications in KCNQ2-related epilepsy, as well as sodium channel blockers." (PMID 39796146, 2024). "On the other hand, it is more difficult to speculate on the role of KCNQ2, which is mainly expressed in neurons and involved in epilepsy." (PMID 37175481, 2023).
epilepsy (continued). "We next tested whether a correlation between sex hormones and mRNA association with the RISC could also be observed for other voltage-gated potassium channels involved in epilepsy, using Kcnq2 and Kcnq3 (called Kv7.2 and Kv7.3, respectively) as examples." (PMID 37433683, 2023). "The relationship between genotype and phenotype in KCNQ2-related epilepsy is not fully understood." (PMID 37497102, 2023). "Retigabine, the anticonvulsant that works by negative-shifting the voltage dependence of KCNQ2/3 channel activation, is effective in forms of epilepsy not caused by KCNQ2/3 channel dysfunction, as well as those that are74." (PMID 37280215, 2023). "67% (6/9) of the patients with KCNQ2-related epilepsy were female." (PMID 36849527, 2023). "Using a mouse model of KCNQ2-related epilepsy, a recent study showed that ESL could dose-dependently exert the protection efficacy from seizure." (PMID 35911890, 2022). "Herein, we reported two cases of KCNQ2-related epilepsy, a 5-year-old male with a paternally inherited heterozygous mutation (c.1639C>T; p.Arg547Trp), and a 10-year-old female with a de novo heterozygous mutation (c.740C>T; p.Ser247Leu), who benefited from PN treatment." (PMID 35401395, 2022). "These cells share neuronal genes expressed in central excitatory neurons such as Kcna1, Kcnq2, Kcnq3, Scn1a, Scn8a, genes that are relevant to epilepsy." (PMID 36192157, 2022). "After searching in DrugBank, we retrieved a total of 47 anti-epileptic drugs and 151 targets, of which identified 17 target genes (CACNA1A, CHRNA4,CHRNA7,GABRA1,GABRA2,GABRB2,GABRG2,GRIK1,GRIN1,GRIN2B,KCNQ2,KCNQ3,SCN1A,SCN2A, SCN3A,SCN8A and SCN9A) were overlapped with risk genes of epilepsy." (PMID 36006933, 2022). "Thirty-five patients manifested epilepsy without any other comorbidity and seven of them (20.0%) carried variants in six genes, namely KCNQ2, NALCN, PAK3, PRRT2, SCN1A, and SLC2A1 that are among the well-known genes causing epilepsies or syndromes including epilepsy." (PMID 36035117, 2022). "Because pathogenic KCNQ2 variants associated with epilepsy are heterozygous, we assessed the functional properties of each variant expressed in this context by cotransfecting CHO-Q3 cells with equal amounts of WT and variant KCNQ2 plasmids." (PMID 35104249, 2022). "In addition, recent reports have been unraveling a potential correlation between KCNQ2-related epilepsies and VitB6 responsiveness." (PMID 35401395, 2022). "Unfortunately, this correlation is currently hindered by the paucity of published clinical drug response data, heterogeneity in dosing among reported cases, and the lack of controlled trials in KCNQ2-associated epilepsy." (PMID 35104249, 2022). "KCNQ2/3 is regulated by a number of small molecules, and new compounds are being specifically developed to open KCNQ2/3 channels with the aim of preventing or treating epilepsy." (PMID 34318654, 2021). "Studies of children with Dravet syndrome and KCNQ2-associated epilepsy also found no clear correlation between seizure burden and cognitive measures." (PMID 34517877, 2021). "Importantly, >300 dominant mutations in KCNQ2 and KCNQ3 cause epilepsy including benign familial neonatal epilepsy (BFNE) and epileptic encephalopathy (EE; Rikee and ClinVar database)." (PMID 33071824, 2020). "Importantly, de novo dominant mutations in their neuronal subunits KCNQ2/Kv7.2 and KCNQ3/Kv7.3 are associated with epilepsy and neurodevelopmental disorder characterized by developmental delay and intellectual disability." (PMID 33071824, 2020). "Since epilepsy likely encompasses unknown genetic changes, the finding of KCNQ2 effects in epilepsy, indicates overlap between known gene changes in infantile epilepsy and unknown gene changes in epilepsy." (PMID 32751954, 2020). "The precise genotype–phenotype correlation in KCNQ2-related epilepsy is not fully understood." (PMID 32770121, 2020).